TIMP1 (TIMP metallopeptidase inhibitor 1)
Diseases named in the same sentence as TIMP1 in open-access papers (continued):
Sharing a sentence is not in itself a finding about the gene and the disease.
breast carcinoma (continued). "TIMP1 overexpression has been described in different types of human cancer, including prostate cancer, lung cancer, melanoma, glioblastoma and breast cancer." (PMID 32012729, 2020). "The high expression of TIMP1 has also been correlated with adverse prognosis in breast carcinoma." (PMID 32539808, 2020). "Furthermore, uptake of TIMP‐1 in breast cancer cells has also been reported in co‐culture systems, suggesting that cancer cells can bind and internalize exogenous TIMP‐1." (PMID 31545548, 2019). "Possible participation of TIMP-1 in angiogenesis was reported in breast carcinoma cells in vivo, and overexpression of VEGF may have an important role in this TIMP-1-mediated effect." (PMID 30458003, 2018). "Interestingly, the tissue inhibitor of metalloproteinase 1 (TIMP1) was highly expressed in SKBR7 breast carcinoma cells." (PMID 29367702, 2018). "While the epithelial cell-derived TIMP1 seem to favor cell survival and inhibit apoptosis, stromal cell-derived TIMP1 secretion may inhibit breast cancer progression." (PMID 28333977, 2017). "In this study, we found that TIMP-1 expression was elevated in TNBC cell lines and TNBC patients compared with non-TNBC cells and non-TNBC breast cancer patients and that increased TIMP-1 expression was associated with a poor prognosis in TNBC patients." (PMID 27130446, 2016). "Specifically, the TIMP1 could degrade cyclinB1 and activate the NF-kβ signaling pathway to protect breast cancer cells against chemotherapy-induced cell death." (PMID 27644693, 2016). "Several tumor-suppressive genes such as BRCA1, TIMP1 and ERα are hypermethylated in breast cancer." (PMID 26418898, 2016). "As for breast cancer, the TIMP-1 genotype has not been found to contribute to breast cancer risk yet." (PMID 26872812, 2016). "Emerging evidence indicates that TIMP-1 is frequently overexpressed in several types of human cancers, including prostate cancer, lung cancer, melanoma, glioblastoma and breast cancer." (PMID 27130446, 2016). "In this study, we analyzed the differences in the immunoreactivity of MMPs (MMP-1, 2, 7, 9, 11, 13, and 14) and TIMPs (TIMP-1, 2, and 3) in breast carcinoma representing three subtypes, luminal A, HER2-overexpressing, and basal-like, based on immunohistochemical findings." (PMID 25510449, 2014). "Moreover, breast cancer patients with TIMP-1 positive cancer cells seem to benefit less from adjuvant anthracycline-containing chemotherapy." (PMID 24884504, 2014). "In the current study TIMP-1 expression was exclusively evaluated in breast cancer cells, and the outcome might have been different if TIMP-1 had been evaluated in stromal cells or in stromal as well as cancer cells." (PMID 24884504, 2014). "Although the mechanism of action of the TIMP-1 C-terminal domain is still unknown, TIMP-1 has previously been shown to bind to cell surface receptors on both fibroblasts and MCF-7 breast cancer cells, which resulted in translocation of TIMP-1 into the cell." (PMID 24616631, 2014). "The results presented here need further validation in order to obtain convincing evidence that TIMP-1 may be used as a predictive marker to direct the use of G in combination with D for patients with advanced breast cancer." (PMID 24884504, 2014). "The use of different methodologies and regimens does compromise the comparability of studies, and thus, the prognostic significance of TIMP-1 in advanced breast cancer remains unclear." (PMID 24884504, 2014). "Moreover shed SDC-1 inhibits alveolar epithelial wound healing, promotes fibrogenesis, and decreases invasion of TIMP-1-sensitive breast cancer cell invasion." (PMID 24551591, 2014). "Moreover, a previous study suggested that when analyzing TIMP-1 in breast cancer tissue, it is the fraction of TIMP-1 in complex with other molecules that is associated with poor prognosis." (PMID 24330623, 2013).
breast carcinoma (continued). "TIMP-1 protein translation was suppressed using an anti-sense morpholino construct designed to specifically inhibit protein translation of TIMP-1 transcript, which reduced the levels of TIMP-1 protein secreted by MDA-MB-231 breast cancer cells through at least 72 hr." (PMID 22957045, 2012). "Moreover, TIMP-1 silencing by antisense technology blocked NO-induced PI3k/Akt/BAD phosphorylation in cultured MDA-MB-231 human breast cancer cells." (PMID 22957045, 2012). "Thus, studies have implicated the TIMP-1/CD63/integrin complex in the regulation of FAK/PI3k/Akt and downstream pro-survival signaling in breast cancer." (PMID 22957045, 2012). "Besides the predictive information, which can apparently be gained from TIMP-1, several publications demonstrate that high levels of TIMP-1 protein in breast cancer tissue, plasma and serum are associated with a poor prognosis." (PMID 19744322, 2009). "Clearly, further studies are required, particularly in view of the emerging theme of TIMP-1 supporting tumour progression in lymphomas, colorectal carcinoma, carcinoma of the breast, and skin tumorigenesis." (PMID 15928670, 2005). "Furthermore, TIMP-1 and TIMP-2 over-expression has been associated with malignant breast tumor behaviour in vivo." (PMID 16168111, 2005). "Accordingly, increasing evidence demonstrates that TIMP-1 is overexpressed in several types of human cancers, including lung cancer, colon cancer, prostate cancer, melanoma, glioblastoma and breast cancer, and its increased expression is correlated with a poor prognosis of the patient." (PMID 37443843, 2023). "TIMP1 is a natural collagenase inhibitor that can inhibit apoptosis, induce angiogenesis, and stimulate cell proliferation, which may be directly involved in the progression and metastasis of cancers such as GC, breast cancer, and colon cancer." (PMID 35938042, 2022). "Additionally, PI3K, MEK, p38 and cyclin D1 activation has been described as result of TIMP1 activity in different breast cancer cells, including MDA-MB-231, providing the molecular basis mediating the proliferation inhibition observed in our experimental models." (PMID 32012729, 2020). "The physiologic receptor of TIMP-1 remains unclear; therefore, further investigation into TIMP-1 receptors and the intracellular processes mediated by TIMP-1 might provide novel insights into the molecular mechanisms of TIMP-1 in breast cancer cells or other types of cancer cells." (PMID 27130446, 2016). "On the other side, it has been demonstrated that TIMP-1 may inhibit apoptosis in breast epithelial cells and promotes cell growth, tumorigenesis, and angiogenesis in different cell types, including breast carcinoma cell lines." (PMID 21745383, 2011). "STAT3 activation may modulate tumor invasiveness of breast cancer by regulating TIMP1 expression." (PMID 21152266, 2010). "Indeed, in contrast to the initial simple biochemistry-based hypothesis, TIMP-1 is viewed as a promising marker to predict poor prognoses of human breast cancer." (PMID 18373849, 2008). "The antiapoptotic effect of TIMP-1 induced by various apoptotic agents has been demonstrated in several different cell types such as human breast epithelial cells, human breast carcinoma cells, human endothelial cells, hepatic stellate cells and Burkitt's lymphoma cells." (PMID 17047657, 2006). "In breast cancer, AJ ethanol extract can inhibit tumor invasion by inhibiting MMP-2/-9 mRNA expression and upregulating TIMP1/2 mRNA expression." (PMID 39630250, 2025). "Immunohistochemical validation via the Human Protein Atlas confirmed elevated TIMP1 protein levels in CRC, breast cancer, glioma, hepatocellular carcinoma, and gastric adenocarcinoma, underscoring its pan-cancer relevance." (PMID 40145096, 2025). "To confirm that a physical interaction between TIMP‐1 and CD74 does take place in breast cancer cells, we performed co‐immunoprecipitation studies using MDA‐MB‐231 breast cancer cells cultured in the presence of rTIMP‐1." (PMID 37081824, 2023).
breast carcinoma (continued). "Through down-regulating MMP-9 and increasing TIMP-1, coptisine can suppress adhesion, migration, and invasion of MDA-MB-231 breast cancer cells." (PMID 36831555, 2023). "To determine the applicability of our findings to a broader context, we analyzed a breast cancer patient cohort for expression of CD74, CD63, and TIMP‐1 by immunohistochemistry (IHC)." (PMID 37081824, 2023). "Following the expression profile of TIMP‐1, the activity of MMP‐1 was significantly lower in spheroids with hASCs and breast cancer cells than in spheroids from other models, while the activity of MMP‐9 was similar among spheroids." (PMID 35600659, 2022). "The RNA level of TIMP‐1 showed a similar pattern; TIMP‐1 expression in hASCs was significantly increased by the 3D spheroid formation and co‐culturing with breast cancer cells, as compared to that in hBMSCs and hDFs." (PMID 35600659, 2022). "BCSCs express TIMP-1 that synthesizes the ligand CD63, further regulates the survival and induces EMT (epithelial-mesenchymal transition) of breast cancer cells." (PMID 34611125, 2021). "We chose TIMP1 for a functional characterization because of its relevance for EMT and cancer progression in other breast cancer subtypes." (PMID 32012729, 2020). "Genistein shows an inhibitory effecton invasion of breast cancer cells in vitro and downregulates MMP-9 expression and upregulates TIMP-1 expression." (PMID 31359993, 2019). "Reciprocally, we isolated MRX7A, SDF2, TFPI2 and TIMP1 specifically from H1299RASSF1A ECM which, conversely to above, are positively correlated with overall survival in lung adenocarcinoma or breast cancer patients (Fig EV2A)." (PMID 31268606, 2019). "In the abstract presented at the San Antonio Breast Cancer Symposium in 2016, only serum activin A, CAIX, HER2 and TIMP1 were described as prognostic for survival." (PMID 30783124, 2019). "The role of TIMP1 in CAA regulation and ECM remodeling should be investigated further to address its role in breast cancer microenvironment." (PMID 28333977, 2017). "A positive correlation between TIMP-1 and CA15–3 concentrations in a group including 100 breast cancer patients (stages I-IV) (R = 0.28) has also been previously revealed." (PMID 28662671, 2017). "Bioinformatics analysis indicate that peptides 1.3(7/52) (PRWAVSP) and 6.2(9/17) (DTFNSFGRVRIE) specifically target TIMP-1 and PAI1, respectively, with both biomarkers being related to breast cancer and to MDA-MB-231 cells." (PMID 27842517, 2016). "TIMP-1 is the tissue inhibitor of MMP-9, which negatively regulating MMP-9 enzyme activity were involved in several tumor metastasis processes, including breast cancer." (PMID 25888829, 2015). "In particular, IFNγ, leptin, TGFβ1, TIMP1, TIMP2, thrombopoietin and VEGF levels were significantly inhibited by anandamide in the conditioned medium of MDA-MB-231 breast cancer cells." (PMID 25147760, 2014). "In mice transgenic for the gelatinase B/MMP-9 inhibitor TIMP-1, paradoxical effects have been described, with high circulating TIMP-1 inhibiting DMBA-induced mammary tumour growth, blocking tumorigenesis at an early stage." (PMID 24473089, 2014). "Concentrations of both Matrix metalloproteinase-9 (MMP-9) and the naturally occurring Matrix metalloproteinase (MMP) inhibitor, Tissue inhibitor of metalloproteinases-1 (TIMP-1), have been investigated as tumor biomarkers in breast cancer." (PMID 24330623, 2013). "The MMP-9:TIMP-1 complex was measured with ELISA and with PLA in plasma samples obtained preoperatively from 465 breast cancer patients." (PMID 24330623, 2013). "PPARγ and RAR ligands inhibited human breast cancer cells proliferation, cell invasion, MMP-9 activity and up regulation of TIMP-1 expression." (PMID 24098526, 2013).
breast carcinoma (continued). "The mean level of MMP-9:TIMP-1 measured by ELISA in the 465 breast cancer plasma samples was 3.63 ng/mL (0.11 – 14.77 ng/mL) and the mean level of MMP-9:TIMP-1 measured by PLA in the 465 breast cancer plasma samples was 0.35 nM (0.09 – 3.50 nM)." (PMID 24330623, 2013). "We performed gelatin zymography to measure the MMP-2 and MMP-9 activities and Western blot to examine the TIMP-1, TIMP-2, MMP-2 and MMP-9 expressions in breast cancer cells." (PMID 23533649, 2013). "Therefore we addressed this by studying the complex of TIMP-1 and pro-MMP-9/MMP-9 and in the present study of 465 breast cancer patients we were not able to find support for the hypothesis that the concentration of MMP-9:TIMP-1 complexes is indicative of prognosis in breast cancer patients." (PMID 24330623, 2013). "For this reason, we first analyzed the mRNA expression levels of MMP-2, MMP-9, MMP-14, TIMP-1, TIMP-2, TIMP-3 and RECK, in the same panel of five human breast cancer cell lines, but now maintained in culture until achieving 80-90% confluence." (PMID 22260435, 2012). "Surprisingly, high TIMP-1 and TIMP-2 mRNA levels can predict adverse prognosis and be correlated with tumor aggressiveness in several different human cancers, including breast cancer." (PMID 21726449, 2011). "Breast cancer cells secrete much higher level of M-CSF, OSM, MIP-2/CXCL-2, MMP-9 and TIMP-1 than ES cells, which are factors correlated with tumor metastasis." (PMID 22174624, 2011). "Evaluation of the activities of TIMP-1, TIMP-2 and TIMP-3 in canine mammary tumor samples by reverse zymography has shown that low activity can be correlated with a malignant phenotype." (PMID 21726449, 2011). "These conclusions are supported by a decreased secretion of TIMP-1 in MCF-7 breast cancer cells overexpressing soluble Sdc-1 ectodomain, supporting breast cancer invasiveness." (PMID 21044331, 2010). "Surprisingly, high levels of TIMP-1 and TIMP-2 have also been shown to predict adverse prognosis and correlate with tumor aggressiveness in several different human cancers, including breast cancer." (PMID 19144199, 2009). "To further address a possible role for MMPs in IL-17-dependent invasiveness of breast cancer cell lines, we assayed the supernatants from IL-17-treated and control MDA-MB231 and MDA-MB453 cells for the presence of MMP-2, MMP-3, MMP-9 and TIMP-1." (PMID 19014637, 2008). "Matrix metalloproteinase-1 was immunohistochemically detected in 88.3% of breast carcinomas, MMP-2 in 42%, MMP-7 in 87.4%, MMP-9 in 74%, MMP-11 in 89.3%, MMP-13 in 73.3%, MMP-14 in 90%, TIMP-1 in 95%, TIMP-2 in 87% and TIMP-3 in 82.3%." (PMID 17848954, 2007). "Monocyte MMP-2 enzymatic activity and MMP-2 as well as TIMP-1 and TIMP-2 protein levels were increased in response to soluble factors from MCF-7 and MDA-MB-231 breast cancer cells." (PMID 16168111, 2005). "To determine whether CD74 expression correlated with that of TIMP‐1 breast cance, we examined TIMP‐1, CD74, and CD63 protein levels in tumor cells in a set of 43 breast cancer tumors." (PMID 37081824, 2023). "We verified that CD74 interacts with TIMP‐1 in breast cancer cells and that this interaction contributes to cellular internalization of TIMP‐1 and mediates intracellular signaling through the Akt signaling axis in breast cancer cells." (PMID 37081824, 2023). "In the past, TIMP-1 was considered to be a negative regulator of tumor metastasis, but more and more studies have found that high expression of TIMP-1 in NSCLC, colorectal cancer, breast cancer, gastric cancer, prostate cancer, endometrial cancer and so on often with poor prognosis." (PMID 36690987, 2023). "Independent of its inhibitory effect on MMPs, TIMP‐1 acts as a growth factor that promotes cell proliferation and tumorigenesis in various cell types, including breast cancer cells." (PMID 35600659, 2022). "In the case of hBMSCs or hDFs, co‐culturing with breast cancer cells did not have a significant effect on TIMP‐1 protein levels." (PMID 35600659, 2022).
breast carcinoma (continued). "We, therefore, speculate that ANXA2, HSPB1, and TIMP1, may be among the genes induced by ZEB1 during early/partial EMT stages that may change the tissue tropism of ERα+ breast cancer cells." (PMID 35440541, 2022). "The negative prognostic impact of serum TIMP-1 as well as tissue protein levels was observed in breast cancer and other cancers." (PMID 35818030, 2022). "In human breast cancer cells with high metastasis potential, coptisine exerts antimetastatic function by downregulation of MMP-9 in combination with increases in tissue inhibitor of metalloproteinase 1 (TIMP-1)." (PMID 35046810, 2021). "A change in TIMP1 expression could mediate resistance to gemcitabine in pancreatic cancer, to fulvestrant in MCF-7 human breast cancer cells, to platinum in epithelial ovarian cancer, to carboplatin in lung cancer, and to antiestrogen in breast cancer." (PMID 34737677, 2021). "MiRNAs are also involved in the downregulation of TIMP-1 and TIMP-3 in breast cancer." (PMID 34445715, 2021). "Consistent with this, a lack of TIMP1 immunostaining is related to improved prognosis in patients with lymph node-positive high-grade breast cancer." (PMID 32420905, 2020). "The promotion of cancer proliferation by TIMP1 activity has been described in other tumor types as leukemias, colon, gastric or breast cancer, but never until now in ovarian cancer." (PMID 32423054, 2020). "Another study on breast cancer showed an association between MMP8 levels and the levels of metalloproteinase inhibitor 1 (TIMP-1) and MMP9 but not with tissue plasminogen activator, urokinase or their inhibitor (PAI-1)." (PMID 31514474, 2019). "TIMP‐1 interacts with a complex of the tetraspanin cluster of differentiation 63 (CD63) and integrin β1 at the cell membrane, and CD63 down‐regulation decreases TIMP‐1 presence at the cell surface and reduces cell survival in breast cancer cells." (PMID 31545548, 2019). "In addition to SNAIL1 effects, LOXL2 influences expression of SPARC and the extracellular proteins TIMP1 and MMP9; in fact, LOXL2 was noted as prognostic factor in breast cancer." (PMID 28425924, 2017). "TIMP1, a known transcriptional target of STAT3, carries complex regulatory role in breast cancer." (PMID 28333977, 2017). "In MDA-468 cells treated with exogenous TIMP-1 (100 ng/mL, Cat#: 970-TM, R&D systems), Akt phosphorylation (primarily at Ser473) increased within 5 min, suggesting that the Akt signaling pathway is involved in TIMP-1-induced breast cancer cell proliferation." (PMID 27130446, 2016). "To gain new insights into the role of TIMP-1 during breast cancer progression, we examined TIMP-1 expression levels in serum derived from breast cancer patients and evaluated the prognostic value of TIMP-1 using a large publically available clinical microarray database of breast cancer specimens." (PMID 27130446, 2016). "Barx2 increased expression of both ESR1 isoforms, the estrogen-responsive genes (SOX5, RBM15 and Dynein), the tissue inhibitor of metalloproteinase (TIMP) genes (TIMP1 and TIMP3), and MMP-9, all of which promote breast cancer cell growth, survival, and invasion." (PMID 27533254, 2016). "We found that higher levels of TIMP-1 expression were associated with poor overall survival (OS) in TNBC patients (p = 0.032) but not in the overall breast cancer population or in the other subtypes evaluated (p > 0.05)." (PMID 27130446, 2016). "We subsequently performed an angiogenesis protein array and found that CXCL16, amphiregulin and tissue inhibitor of metalloproteinases (TIMP1) were expressed at high levels in the TN but not the ER+ breast cancer CAF supernatants." (PMID 27725631, 2016). "But in our study, TIMP-1 expression was not seemed to be the regulator of MMP-9 activation in breast cancer cells." (PMID 25888829, 2015). "TIMP-1 status was an independent prognostic factor for OS but not TTP in patients with advanced breast cancer receiving either D or GD." (PMID 24884504, 2014).